PIK3R1 (phosphoinositide-3-kinase regulatory subunit 1)
Diseases named in the same sentence as PIK3R1 in open-access papers (continued):
Sharing a sentence is not in itself a finding about the gene and the disease.
tumor (continued). "Analysis of PIK3R1, PIK3R3 and PIK3CA mRNA expression in these datasets revealed that PIK3R1 was significantly down-regulated in PCa tumours relative to normal tissue in 9 of the 10 studies." (PMID 26501081, 2015). "We also used web-driven software to identify potential gene targets of these key miRNAs and found that two of virtually predicted miRNA target genes, PIK3R1 and MMP-2, were promising anti-tumor targets in CCA cell signal pathways." (PMID 24147037, 2013). "We found that expression of PIK3R1, PIK3R3, and AKT3 significantly enhanced 6.27-, 9.78-, and 4.53-fold respectively in tumor tissues in comparison with arachnoidal tissue by qRT-PCR." (PMID 23285163, 2012). "Five miRNAs (19b, 29a, 29b, 29c and 148a) shared 70 predicted targets, some of which (CDK6, PTEN, IGF1, FRS2, PDGFRA, PIK3R1 and MXD1) regulate cellular proliferation and tumor suppression." (PMID 20949028, 2010). "Overall, histone modifications of PIK3R1 may enhance p85α expression, thus activating the PI3K/AKT pathway and potentially contributing to tumor chemoresistance." (PMID 40657399, 2025). "Specifically, the NR3C2, ANPEP, and FCGRT genes were significantly upregulated in tumor tissues, while PIK3R1, MME, SCD, and SERPINE1 genes were notably downregulated." (PMID 41011246, 2025). "PIK3R1, also known as phosphoinositide 3‐kinase regulatory subunit 1, is an important regulatory subunit in the PI3K/AKT pathway, which is widely regarded as a key signaling pathway in tumor cells." (PMID 40244859, 2025). "PDGFRA activation leads to phosphorylation of PIK3R1, triggering downstream signaling cascades including calcium mobilization and activation of PKC, AKT1, HRAS/MAPK/ ERK, and STAT pathways, thereby promoting tumor growth and survival." (PMID 41426972, 2025). "Furthermore, the present study found a strong correlation between the expression of target genes (IL10RB, INHBB, NEO1, PIK3R1, BCL2, ID4, and INHBA) and the infiltration of tumor-killing cells into the tumor immune microenvironment in HNC." (PMID 40647469, 2025). "In addition, Lnc-PIK3R1, transcriptionally repressed by YY1, suppresses HCC progression through the Lnc-PIK3R1/miR-1286/GSK3β axis, highlighting its tumor-suppressive role." (PMID 40789840, 2025). "The random forest model predicts that cinnamic acid has significant anti-tumor activity (probability = 0.69), which inhibits Hep3B cell proliferation (IC50 = 33.70 μM) and migration by targeting the PI3K/AKT signaling pathway (core targets PIK3R1, AKT1)." (PMID 40872596, 2025). "Interestingly, MC5 (PIK3R1, ITPR2, LRP2) was mainly seen in pre-treatment tumor cells of positive immune state change group." (PMID 38714665, 2024). "The PPI network analysis, informed by topological parameters, suggested that PIK3R1, SRC, AR, and MMP9 could be considered as key target genes for the combined anti‐tumor immunity effects of Danggui and Huangqi." (PMID 38863309, 2024). "p85α/PIK3R1 is a negative pathway regulator, and its disruption is likely to lead to increased pathway activity and downstream tumor-promoting mechanisms." (PMID 38489912, 2024). "Mechanically, IL-23 and PD-1 mAb both decrease the expression of Phosphoinositide-3-Kinase Regulatory Subunit 1 (PIK3R1), which is a regulatory subunit of PI3K and inhibit p110 activity, thereby promoting the subsequent activation of AKT pathways in tumor-specific cytotoxic T lymphocytes (CTLs)." (PMID 38902343, 2024). "Additionally, when comparing the findings from tumor samples that underwent testing using the expanded panel testing to the TCGA-UCEC cohort, a higher altered frequency of PIK3R1 and CTCF was identified in the TCGA cohort." (PMID 37730563, 2023). "Besides, this study also suggested that APA profiles of some clinically actionable genes varied greatly among different tumor types, such as CTNNB1 and PIK3R1." (PMID 35487956, 2022).
tumor (continued). "The results revealed that PIK3R1 and PIK3R2 showed medium staining in most normal tissues, while in most tumor tissues PIK3R1 showed low or negative staining and PIK3R2 showed medium or high staining." (PMID 35395865, 2022). "KRAS-Mut tumors showed significant upregulation of tumor migration (TGFBR2-S553 and EPHB3) and PI3K/AKT activation (PIP4K2C and PIK3R1), while the KRAS-WT group was enriched in immune regulation (TAP1/2, IFITM1, and IFIH1-S301) and cellular metabolism (DGAT1 and HINT3)." (PMID 35836817, 2022). "In contrast to PIK3R1, PIK3R2 was highly expressed in most tumor types, such as BRCA and COAD." (PMID 35395865, 2022). "The hub genes, including PIK3R1, CTNNB1, JUN, EGFR, and APP, might play an important role in tumor development." (PMID 35733630, 2022). "In spite of the extensive knowledge on class I PI3K, until recently, the function and mechanism of PIK3R1 in the proliferation and invasion of malignant tumours are not clear." (PMID 34741385, 2021). "With the exception of clonal Pdgfra and Nav3 insertions in one tumor, transposon insertions in MAPK/PI3K pathway and neurodevelopmental genes (including Nf1, Pten, Pik3r1, Ptprj, Sox6, Sox5, and Tcf4) were subclonal in these tumors, implying these were late evolutionary events." (PMID 32727536, 2020). "PIK3R1 (also known as PI3K p85α), a regulatory subunit of PI3K, has been reported to play an inhibitory role in the activation of the PI3K/Akt signaling pathway and suppress tumor progression." (PMID 32366257, 2020). "The re-biopsied tumour at resistance was PIK3CA wt but had low PIK3R1 expression and acquired an IRS1 P313S variant that was not present in the sensitive tumour." (PMID 31653970, 2019). "The number and weight of peritoneal disseminated tumor nodules formed by SKOV3 cells expressing PIK3R1-shRNA, but not vector control, were markedly decreased after the inhibitor treatments." (PMID 30755611, 2019). "In response to doxycycline, the cells showed reduced PIK3R1 levels, although this treatment did not significantly reduce tumor size." (PMID 27835880, 2016). "Notably, ITGB8, DICER1, INPP5A, PIK3R1, and TIMP2 are key tumor suppressors that were among up-regulated CRGs following CBX2 knockdown." (PMID 26877821, 2016). "Among the genes that are mutated between 5 to 20% in TCGA GBM tumor samples, we found mutations in NF1, SPTA1, TCHH and ATRX genes, although, the other genes like PIK3R1, PIK3CA, RB1, IDH1 and KEL were not mutated in any cell line." (PMID 26496030, 2015). "The analysis of the genetic status of PIK3R1 by Q-PCR failed to reveal an increase in the copy number of the PIK3R1 gene in the 30 tumor analysed." (PMID 23408974, 2013). "Of notice, study patients demonstrating high tumor PI3K-mediated signaling activity, as all array substrates of this specific pathway (PIK3R1, CTTN1, PLCG1, PDPK1, and RASA1) were highly phosphorylated, had particularly poor metastasis-free survival after radical treatment of the pelvic cavity." (PMID 23226389, 2012). "Furthermore, expression of PIK3R1 (phosphatidylinositol 3-kinase regulatory subunit alpha, p85α) was downregulated 6.5-fold, which may indicate aberrant activity of PI3K in DC-tumor fusion cells." (PMID 26605345, 2015). "Our results indicated that expression levels of miR-29b, miR-125a-5p, miR-205, and miR-221 may be useful as diagnostic markers of sensitivity to Gem treatment, and that PIK3R1 and MMP-2 could become molecular targets of anti-tumor therapies for patients with CCA." (PMID 24147037, 2013). "An analysis of the correlation between UHRF1 expression and that of its target genes in scT‐LBLs demonstrated that the tumour suppressor genes FOXP1, PIK3R1 and KLF6 exhibited a significant negative correlation with UHRF1 expression." (PMID 40579780, 2025).
tumor (continued). "The top negative DEGs, including ABCB1, SPRY1, EREG, PIK3R1, SPTBN1, VIM, KDR, and others, exhibit a negative correlation with tumor purity while demonstrating a strong positive correlation with T‐cell infiltration, especially CD8+ T cells." (PMID 40567015, 2025). "Firstly, IHC staining revealed that PIK3CA was strongly positive in TPMCa tumors, while PIK3R1 is negative in TPMR1 tumors, indicating that the tumor cells originate from a specific genotype of organoids." (PMID 37340596, 2023). "In addition, statistical results showed that PIK3R1 expression was closely associated with lymphatic metastasis (p = 0.029), distal metastasis (p = 0.004) and pathologic tumor, node, metastasis stage (TNM stage, p = 0.002), but not age (p = 0.548), gender (p = 0.484) and tumor size (p = 0.503)." (PMID 30497511, 2018). "As mentioned, PIK3R1 also acts as a negative modulator of PIK3CA and has been shown to have tumor suppressor activity." (PMID 21533174, 2011). "Our study discerned that miR‐21‐related genes, such as ABCB1, SPRY1, ERGE, PIK3R1, SPTBN1, VIM, and others, which experienced downregulation in tumor sites, exhibited a negative correlation with tumor purity and a positive association with T cell infiltration, notably CD8+ T cells." (PMID 40567015, 2025).
cancer (241 papers, 2007 to 2026). A tumor composed of atypical neoplastic, often pleomorphic cells that invade other tissues. "PIK3R1 mutations across different domains exhibit varying impacts on cancer, necessitating diverse therapeutic strategies for effectiveness." (PMID 40657399, 2025). "For example, a 2023 case study of a patient with cancer independent SS identified a gain-of-function PIK3R1 mutation—specifically in neutrophils—that increased neutrophil migration and respiratory burst capacity." (PMID 40516577, 2025). "Aberrations in the PIK3R1 gene are associated with poor prognosis in cancer; available data underscore the significant role of PIK3R1 mutations in mediating tumorigenesis by promoting the signaling of the PI3K/AKT/mTOR pathway." (PMID 40657399, 2025). "The phosphatidylinositol 3-kinase signaling pathway is known to be involved in cancer, and PIK3R1 has shown association with risk in CRC." (PMID 39859530, 2025). "This article reviews the cancer-promoting effects of PIK3R1 gene aberrations across major cancer types and elucidates their underlying mechanisms." (PMID 40657399, 2025). "Other “Tier 1” cancer-related gene mutations in the COSMIC Cancer Gene Census21 present in the 15 most frequently mutated genes include PIK3R1 (4%), NF1 (4%), NOTCH1 (4%), APC (3%), and ATR (3%)." (PMID 40057511, 2025). "Tumors with PIK3R1 mutations mostly represented low-stage cancers of endometrioid and clear-cell type." (PMID 39858051, 2025). "Copy number variations, mutations, and epigenetic alterations in PIK3R1 contribute to a proliferative phenotype characterized by recurrent mutations across diverse cancers." (PMID 40657399, 2025). "Cancer-associated mutations have been identified across all five protein domains of the PIK3R1 gene." (PMID 40657399, 2025). "Somatic alteration in PIK3R1 comprises an overlapping variant spectrum between vascular malformation and overgrowth to that of cancer in association with the dysregulation of the PI3K enzyme." (PMID 38541623, 2024). "Subsequently, we assessed the mutation frequencies of hub genes in pan-cancer, with PIK3R1 exhibiting the highest frequency of SNV." (PMID 38846934, 2024). "Identifying PIK3R1 mutations in 61.54% of patients further emphasizes the role of the PI3K/AKT/mTOR pathway in this cancer type, supporting the rationale for ongoing research into targeted therapies that inhibit this pathway." (PMID 39296440, 2024). "On the contrary, lower miR-21-5p on upstream of PIK3R1 is associated with a higher surviving rate in cancer patients, P < 0.05." (PMID 36688087, 2023). "Here, we describe the different PIK3CA and PIK3R1 mutations observed in a real-life cohort of 1200 cancer patients." (PMID 36934165, 2023). "The incidence of PIK3R1 (p85 α) mutations are higher in EC compared to any other cancer lineage, and the primary cause for triggering the PI3K pathway is the loss of PTEN protein." (PMID 37583914, 2023). "We found 141 patients (11.8%) with a PIK3CA and/or PIK3R1 mutation across 20 different cancer types." (PMID 36934165, 2023). "We found a total of 135 somatic PIK3CA mutations (among which 38 different mutations, located in various exomes) and 15 PIK3R1 mutations (among which 20% were considered pathogenic because loss-of-function), across 20 different cancer types." (PMID 36934165, 2023). "On the contrary, the lower miR-21-5p on upstream of PIK3R1 is associated with a higher surviving rate in cancer patients (P < 0.05)." (PMID 36688087, 2023). "We determined the incidence and type of all somatic PIK3CA and PIK3R1 mutations by whole exome sequencing (WES) in a pan-cancer cohort of 1200 patients." (PMID 36934165, 2023). "As one of the core members of PI3K pathway, PIK3R1 mutation is the 12th most commonly mutated gene across cancer lineages." (PMID 35395865, 2022).
cancer (continued). "And in most cancers, “mutation” is the primary alteration type of PIK3R1, and the highest alteration frequency of PIK3R1 (31.38%) occurs in cases with UCEC." (PMID 35395865, 2022). "PIK3R1 somatic cell mutation has a similar mechanism to cancer-related mutation, which leads to complex vascular malformation and overgrowth." (PMID 36060002, 2022). "Somatic PIK3R1 variants sharing attributes with cancer-associated variants cause complex vascular malformations and overgrowth." (PMID 34040190, 2021). "Disease-associated PIK3R1 variants are enriched for indel events in both cancer and vascular anomalies with overgrowth." (PMID 34040190, 2021). "Many other targets of miR-455-5p have been reported, such as galectin-9 and PIK3R1 and these interactions have been implicated in cancer development." (PMID 33962657, 2021). "In cancer, loss of PIK3R1 has been shown to promote EMT and cellular proliferation by over-activation of downstream AKT signaling." (PMID 34301992, 2021). "The PI3 kinase complex, consisting of the catalytic component (PIK3CA) and the regulatory component (PIK3R1), has also been implicated in many cancers." (PMID 33237934, 2020). "While NGS analysis unveiled common mutations in PTEN, CTNNB1, and ARID1A, different PIK3CA and PIK3R1 mutations were also detected, suggesting the existence of at least two cancer clones." (PMID 32652986, 2020). "Alterations in the PIK3R1 gene are less common than PIK3CA mutations with an average of 3% across all cancer types." (PMID 30650664, 2019). "In animal models of cancer, liver-specific knockout of PIK3R1 increased the activation of the PI3K pathway and caused tumorigenesis." (PMID 30650664, 2019). "Collectively, these findings underscore the lineage-specific consequences of PIK3R1 loss in cancers." (PMID 30755611, 2019). "This further suggests that PIK3R1 loss promotes tumorigenesis through distinct mechanisms in different cancer types." (PMID 30755611, 2019). "In contrast, FLT3, BRCA1, BRCA2 and PIK3R1 mutations were more frequently detected in patients carrying germline cancer-associated variants." (PMID 30850667, 2019). "Studies of the Pik3r1 gene have described its association with the occurrence and metastasis of cancer." (PMID 28787439, 2017). "Strikingly, PIK3R1, the gene coding for p85α, is the twelfth most frequently mutated gene across all cancers." (PMID 26222500, 2015). "PIK3R1, a regulatory subunit of phosphatidylinositol 3-kinase has been implicated in tumorigenesis and metastasis in various cancers." (PMID 24403257, 2013). "PIK3R1 has been identified as a candidate cancer driver gene and is mutated in ∼9% of GBM patients, but the loss of one allele, as seen here, has not been reported." (PMID 23441165, 2013). "A comprehensive understanding of how PIK3R1 mutations affect their interactions and regulatory functions will aid in identifying cancer-associated mutations that dysregulate the PI3K pathway and pinpoint the most effective therapeutic targets for inhibitor therapy." (PMID 40657399, 2025). "Furthermore, the article explores the cancer-promoting effects of mutations in various domains of PIK3R1." (PMID 40657399, 2025). "Downregulation of PIK3R1 is associated with poor survival outcomes for most cancer patients." (PMID 38846934, 2024). "Therefore, alteration to the PIK3R1 SH2 domain or its interactions with PIK3CA would be consistent with the effects of the cancer hotspot mutations of PIK3CA." (PMID 38541623, 2024).